KLF2 (KLF transcription factor 2)
Diseases named in the same sentence as KLF2 in open-access papers (continued):
Sharing a sentence is not in itself a finding about the gene and the disease.
tumor (145 papers, 2012 to 2026). "The function enrichment analysis of KLF2 targets indicated the crucial association between KLF2 and tumor matrix." (PMID 37386390, 2023). "The function enrichment results of the KLF2 targets, namely KLFTs, indicate that highly enriched entries focus on biological features associated with tumor stroma and immune responses." (PMID 37386390, 2023). "It was reported that KLF2 and KLF6 act as tumor suppressor genes, and downregulation of KLF2 or KLF6 was associated with poor survival in several cancers." (PMID 29290960, 2017). "Collectively, these results revealed that CGRP secreted by tumor cells could drive an abnormal development of intra-tumoral DCs by cAMP pathway activation and preventing the loss of KLF2." (PMID 39030177, 2024). "Furthermore, we examined the correlation between KLF2 and common signaling pathways associated with tumor matrix formation." (PMID 37386390, 2023). "Overall, our results not only validate the chemoprotective effect of the miR-125High subpopulation, but also indicate that the KLF2-mediated epigenetic mechanism underlies the regeneration and persistence of a subpopulation of miR-125High altruists within the tumor." (PMID 38093346, 2023). "Therefore, in the present review, we discussed the molecular mechanisms of the KLF2 during tumor progression to introduce that as a reliable diagnostic and therapetutic target in cancer patients." (PMID 37807067, 2023). "Moreover, KLF2 expression was negatively correlated with tumor mutational burden (TMB) (ρ = − 0.29, P < 0.001)." (PMID 37386390, 2023). "The results revealed that the expression of KLF2/4/9 was associated with the tumor stage." (PMID 35033064, 2022). "We show that 4-1BB antibody targeted delivery of a KLF2 siRNA to vaccine activated CD8+ T cells in tumor bearing mice leads to increased intratumoral content of Trm cells and enhances vaccine mediated inhibition of tumor growth." (PMID 40162209, 2025). "Downregulation of the transcription factor KLF2 is the most conserved molecular feature of Trm, establishing their tissue or tumor residence." (PMID 40162209, 2025). "The KLF2 gene also exhibited an open chromatin state in both normal and tumor tissues, as indicated by DNA hypomethylation and active histone marks." (PMID 39796183, 2025). "In the context of CGRP activating the cAMP pathway, a positive correlation was observed between the cAMP activation score and KLF2 expression in tumor DCs, indicating the potential relationship between changes in KLF2 expression and CGRP receptor activation." (PMID 39030177, 2024). "KLF2 is a transcription factor involved in various biological processes and is discussed as tumor suppressor for several cancer entities." (PMID 39623312, 2024). "For another instance, KLF2 acts as a tumor suppressor in AML, and its upregulation promotes apoptosis and differentiation of AML cells." (PMID 38619693, 2024). "The suppressor gene KLF2 methylation was significantly reduced in NSCLC because of its region 4 methylation associated with lymph node metastasis and advanced tumor stage." (PMID 38560274, 2024). "It has been shown that the KLF2 as a tumor suppressor is mainly inhibited by the non-coding RNAs (ncRNAs) through the polycomb repressive complex 2 (PRC2) recruitment." (PMID 37807067, 2023). "CDK8 was critical for tumor vessel progression in pancreatic carcinoma through the β-catenin-KLF2 axis." (PMID 37807067, 2023). "It has been reported that the KLF2 has mainly a tumor suppressor function that can be suppressed by the oncogenic ncRNAs following the PRC2 recruitment." (PMID 37807067, 2023). "KLF2 was predominantly expressed at high levels in normal tissue than their tumor tissues, such as, breast, kidney, endometrium, stomach, colon, lung, and thyroid gland tissues in TCGA database." (PMID 37123417, 2023). "H3K27me3 enriched in the Kruppel-like factor 2 (KLF2) promoter leads to the tumor cell population in GC and CRC." (PMID 36900163, 2023).
tumor (continued). "In the present review we discussed the molecular mechanisms of KLF2 during tumor growth and invasion." (PMID 37807067, 2023). "RNAseq analysis identified robust upregulation of the transcription factor KLF2 by lovastatin, previously known for its tumor suppressor activity." (PMID 37016335, 2023). "On the other hand, it has been shown that lncRNAs promote PRC2-mediated KLF2 down regulation in tumor cells." (PMID 37807067, 2023). "Non-etheless, one of the limitations of this study is the scarcity of experimental data to comprehensively validate the specific regulatory mechanism of KLF2 in anti-tumor therapy." (PMID 37123417, 2023). "It has been reported that PRC2 complex has a key role in regulation of KLF2 expression in tumor cells via histone methylation in promoter region." (PMID 37807067, 2023). "Multidimensional analyses of the correlation between KLF2 and immune infiltration showed an essential involvement of KLF2 in regulating tumor immune microenvironment." (PMID 37386390, 2023). "Considering that the PRC2 complex as an KLF2 inhibitor has an oncogenic role, PRC2 inhibitors can indirectly inhibit the tumor growth and progression by KLF2 activation." (PMID 37807067, 2023). "Firstly, we analyzed KLF2 expression distribution between different human tumor and normal tissues in TCGA database." (PMID 37386390, 2023). "In other tumor types, patients with high KLF2 expression exhibited a trend of extended survival, albeit without statistical significance." (PMID 37123417, 2023). "KLF2 is mostly observed to have tumor-suppressing effects in HCC cells as it inhibits cell proliferation via suppression of Hedgehog signaling and metastasis via prevention of TGF-β-mediated Smad signaling." (PMID 36902112, 2023). "KLF2 remarkably inhibited tumor cell viability while induced apoptosis through the expression of p15 and p21 in NSCLC cells." (PMID 37807067, 2023). "Numerous studies have shown that the expression of KLF2 is reduced in various cancers, and it plays a role in inhibiting tumor cell proliferation and inducing apoptosis." (PMID 36087568, 2022). "KLF2 is poorly expressed in various cancers and possesses tumour‐suppressive features by repressing cell proliferation." (PMID 35322532, 2022). "Studies have found that KLF2 gene plays a tumor suppressor function by inhibiting TGF-β/Smad signaling in HCC cells." (PMID 36276937, 2022). "To explore dynamic temporal interactions between KLF2 expression in tumor epithelial cells with host plasma cells, we used a humanized mouse cancer in vivo model." (PMID 34642171, 2022). "KLF2 has been proven to be the target of miR-92a-3p and plays an important role in tumor angiogenesis." (PMID 34257272, 2021). "On the basis of the silencing of LINC01232, the expression of KLF2 in SGC-7901 and HGC-27 cells was knocked out, and the results showed that the inhibition of KLF2 was essential for the tumor-promoting effect of LINC01232." (PMID 34409953, 2021). "Although in a previous study KLF2 was reported to be a tumor suppressor that affected cell proliferation in GC, cell proliferation was not affected by either siKLF2 or miR-BART17-5p in the present study." (PMID 32075248, 2020). "Our data suggest that miR-BART17-5p, which is highly expressed in EBVaGC, plays an oncogenic role by inhibiting a tumor suppressor KLF2 expression." (PMID 32075248, 2020). "EZH2 is a factor that can counteract the tumour‐suppressive qualities of KLF2 by binding to its promoter region, silencing KLF2 transcription." (PMID 32420685, 2020). "KLF2 a key tumour suppressor gene of the Kruppel‐like factor (KLF) family, altered expression of which is associated with the progression of numerous forms of cancer." (PMID 32420685, 2020). "For example, the lncRNA ANRIL is able to recruit EZH2 to the promoter region of KLF2, a known tumor suppressor, to induce its epigenetic silencing by trimethylation of the histone H3 at lysine 27 (H3K27me3)." (PMID 32331331, 2020).
tumor (continued). "Specifically, Kruppel-like factor 2 (KLF2), associated gene of lnc-EPS15L1-2:1 from Cis and Trans analyses, was reported as a terminal component of tumor proliferation and metastasis related pathway axis." (PMID 31355249, 2019). "CDKN1A and KLF2 have been identified as novel tumor suppressors involved in cancer cell proliferation, apoptosis, and invasion." (PMID 30367681, 2018). "KLF2, a tumor suppressor and member of the KLF family, contains Cys2/His2 zinc finger motifs and acts as transcription factors to regulate downstream targets including cyclin-dependent kinase genes." (PMID 29642935, 2018). "We further found that egr1, a flow responsive transcription factor gene involved in FGF-dependent angiogenesis during neo-vascularization and tumor growth, is downregulated in klf2 mutant hearts." (PMID 30592462, 2018). "As a member of the Kruppel-like factor family, KLF2 is down-regulated and possesses tumor-suppressor features such as inhibition of cell proliferation and enhancement of DNA-damage-associated apoptosis in many cancers." (PMID 30266084, 2018). "Among these altered genes, KLF2 has been identified as a novel tumor suppressor involved in cancer cell proliferation and apoptosis." (PMID 28938648, 2017). "During the tumor development, we found that knockdown of KLF2 significantly promoted tumor formation in vivo." (PMID 29245984, 2017). "To further testify our prediction, we used tumor transplantation mouse models to evaluate KLF2’s inhibitory effect in vivo." (PMID 29245984, 2017). "Impaired expression of KLF2 markedly promoted cell growth in vitro and significantly expanded tumor size in vivo." (PMID 29245984, 2017). "Impaired KLF2 expression led to tumor growth promotion in vitro and in vivo by activating AKT-mTOR signaling through downregulating PTEN." (PMID 29245984, 2017). "Functionally, KLF2 acted as a tumor suppressor which inhibits cell proliferation and induces cell apoptosis." (PMID 29245984, 2017). "Our findings showed that the trends toward lower expression of KLF2 and higher expression of NOTCH2 were linked tumor progression." (PMID 28887496, 2017). "Consistent with this, impaired expression of KLF2 significantly promoted GC growth in vitro and tumor formation in vivo." (PMID 29245984, 2017). "KLF2 is one of the key members in the Kruppel-like factor (KLF) family due to its tumor suppressor function in malignancies such as breast cancer, non-small cell lung cancer, prostate cancer and leukemia." (PMID 28938648, 2017). "Our results support the possibility that KLF2 acts as a tumor suppressor in gastric tumorigenesis and serves as a potential therapeutic target." (PMID 29245984, 2017). "Recent studies revealed that KLF2 expression is diminished in several human cancers and exhibits tumor-suppressor features for its inhibitory effect on cell proliferation and induction of cell apoptosis." (PMID 28441948, 2017). "As an member of KLF family, KLF2 expression is inactivated or lost in several cancers and possesses tumor-suppressor features mediated by KRAS." (PMID 26336870, 2015). "The data thus reveal that KLF2 suppresses tumor growth by controlling the transcriptional activities of RA." (PMID 26416422, 2015). "We show further that KLF2 suppresses tumor development by controlling the transcriptional activity of the vitamin A metabolite retinoic acid (RA)." (PMID 26416422, 2015). "Then qPCR analysis was performed to detect the average expression of KLF2 in tumor tissues selected from mice." (PMID 26336870, 2015). "Remarkably, all sites injected with parental cells developed tumors, but 2 out of 10 mice injected with KLF2-overexpressing cells remained tumor-free throughout the experiment." (PMID 26416422, 2015). "The results showed downregulation of HOXD3, PRUNE2, CD302, CCDC8, and KLF2 (tumor vs. control)." (PMID 41186818, 2025). "Overexpression of KLF2 has been shown to suppress tumor growth both in vitro and in vivo." (PMID 40740483, 2025).
tumor (continued). "Further integration of our cohort with publicly available single-cell RNA data revealed that in tumor, the activation level of the cAMP pathway in DCs is positively correlated with the expression level of KLF2, while it is negatively correlated with co-stimulatory function." (PMID 39030177, 2024). "Additionally, the KLF2 maintaining tumour cells survival, exhibited heightened regulon activities in CD14+APOE+ cells." (PMID 39187937, 2024). "Notably, in cholangio carcinoma (CHOL), KLF2 expression was higher in tumor tissue than in normal tissue." (PMID 37123417, 2023). "Consequently, we analyzed the expression of KLF2 in mouse tumor tissue treated with simvastatin, which exhibited a significant increase compared to the control group." (PMID 37123417, 2023). "KLF2 has been shown to function as a tumor suppressor through TGF-β/Smad signaling in HCC cells." (PMID 37386390, 2023). "Interestingly, KLFs can exert opposite effects in regulating the same pathways and initiate different cell responses, as some of them can function as tumor suppressors (KLF2, KLF8) and some as oncogenes (KLF7, KLF9)." (PMID 37239940, 2023). "In conclusion, low KLF2 expression promotes the malignant biological behavior of GC, and KLF2 acts as a tumor suppressor and may be a potential therapeutic target and prognostic biomarker for GC." (PMID 36874616, 2023). "Moreover, lovastatin strongly induced the expression of KLF2, known to function as a tumor suppressor gene." (PMID 37016335, 2023). "The results showed that the knockdown of KLF2 could significantly promote the growth, proliferation, migration, and invasion of GC cells, as well as tumor development." (PMID 36874616, 2023). "KLF2 acts as tumor suppressor in NSCLC cells and its’ expression could be repressed through XIST via recruiting EZH2 to its promoter region." (PMID 37807067, 2023). "KLF2 functions as a tumor suppressor by PCNA and CCND1 down regulations while p21 up regulation." (PMID 37807067, 2023). "Studies have shown that KLF2, as a tumor suppressor, is downregulated in many human cancers, but its relationship and role with GC remain unclear." (PMID 36874616, 2023). "Moreover, KLF2 has been demonstrated to be a significantly terminal factor for tumor progress and metastasis in multiple cancers." (PMID 37386390, 2023). "KLF2 functions as a tumor suppressor or oncogene in different tumors." (PMID 37807067, 2023). "Therefore, it is required to use the novel methods to deliver the inhibitors of PRC2/KLF2 axis locally and specifically to the tumor tissue in order to reduce the side effects as much as possible." (PMID 37807067, 2023). "Whereas for the SP1, KLF6, and KLF2, discordant findings have been reported as to whether they play a tumor-promoting or suppressing role in HCC progression." (PMID 36902112, 2023). "Our previous study showed that simvastatin can induce DNA double-strand break repair, and we speculate that simvastatin may affect DNA double-strand break repair in tumor cells by up-regulating KLF2 expression." (PMID 37123417, 2023). "Analysis of surgical samples indicated that the expressing levels of KLF2 and ANXA5 were associated with infiltrating immune cells and the expression of PD-L1 at the immune checkpoint in tumor tissues Our analysis showed that immune microenvironment and tumor immunity serve a crucial part in HCC." (PMID 35992798, 2022). "In NSCLC, KLF2 is downregulated and has a tumor suppressor function." (PMID 36101460, 2022). "The expression level of KLF2 in the tumor epithelial cell depends on its spatial location." (PMID 36313703, 2022). "In addition, double immunofluorescent staining with KLF2 (green) and CD31 (red) showed that injection of exosomes obviously resulted in downregulation of KLF2 in the tumor tissue (white arrowheads) and vessels (orange arrows), compared with the PBS group." (PMID 34257272, 2021).
tumor (continued). "Moreover, the tumor-suppressive effects mediated by sh-LINC00665 were significantly reversed through the down-regulation of KLF2." (PMID 34094920, 2021). "Furthermore, the relative expression of miR-92a-3p and KLF2 was also confirmed in tumor tissues treated with PBS or exosomes." (PMID 34257272, 2021). "It was found that knock-down of KLF2 could counteract the tumor-suppressive effect of the knock-down of LINC00665 on the proliferation and migration ability of PCa cell lines." (PMID 34094920, 2021). "Additionally, the knock-down of LINC00665 triggered a reduction of LINC00665 expression while an increase of KLF2 protein level in excised tumor masses." (PMID 34094920, 2021). "KLF2 is a key mediator of cancer development and tumour progression." (PMID 32420685, 2020). "We therefore selected EZH2 target genes with tumour‐suppressive functions (KLF2, RND1 or PTEN) that could be involved in the link between SNHG7 and OC progression." (PMID 32420685, 2020). "In BTC cells, this complex performs epigenetic silencing of the tumor suppressors KLF2 and LATS2." (PMID 32331331, 2020). "Our data suggest that KLF2 functions as a tumor suppressor in EBVaGC and that miR-BART17-5p may be a valuable target for effective EBVaGC treatment." (PMID 32075248, 2020). "We also have investigated whether KLF2 acts as a tumor suppressor in EBVaGC and affects tumorigenesis." (PMID 32075248, 2020). "As a tumour suppressor, KLF2 suppresses KRAF‐mediated tumour proliferation." (PMID 32420685, 2020). "Indeed, most TIL subpopulations had attributes of tissue residency, including low S1pr1 and Klf2 expression and high Cd69 expression, contrasting with Arm and most tumor dLN clusters." (PMID 31801070, 2019). "Some evidences showed that EZH2 could silence KLF2 expression and inhibit the tumor-suppressor features of KLF2." (PMID 30266084, 2018). "As well characterized previously, FBW7 could also promote the degradation of c-Jun and KLF-2, the two important transcription factors that regulate tumor cell proliferation and invasion." (PMID 30177679, 2018). "In this study, we also found that KLF2 can function as tumor suppressor and its’ expression could be suppressed by DUXAP10 through recruiting PRC2 and LSD1 to its promoter region in GC cells." (PMID 29374493, 2018). "All of these findings support our result that KLF2 functions as a tumor suppressor." (PMID 29245984, 2017). "Indeed, EZH2 has similar effects on tumor cells as KLF2, such as inducing apoptosis and restraining the cell cycle." (PMID 29245984, 2017). "In this study, we also showed that KLF2 can function as tumor suppressor and its' expression could be suppressed by LINC01133 in NSCLC cells." (PMID 26840083, 2016). "In accordance with the notion that the tumor suppressing activity of KLF2 is exerted at least in part by controlling RA signaling, ectopic expression of this factor, similarly to direct alteration of the FABP/CRABP2 ratio, converted RA from a pro- to an anti-proliferative agent." (PMID 26416422, 2015). "Thus, whereas Nfib was reported as an oncogene in the lung due to its high expression in lung tumors, Klf2, Cyr61 and Ctgf were considered tumor suppressor genes due to their reduced levels." (PMID 24391734, 2013). "In addition, KLF2, a transcription factor which is downregulated in TRM to promote the formation of CD69 was found it underlies the regeneration and persistence of a subpopulation of miRNA -125Highbreast tumor cells via an epigenetic way." (PMID 40895552, 2025). "The higher KLF2 expression may indicate the mobility of γδ tumor-infiltrating lymphocytes (TILs)." (PMID 39454432, 2024). "Hence, our data suggest that KLF2 may serve as a tumor suppressor gene in the majority of common tumors." (PMID 37123417, 2023). "Therefore, inhibition of lncRNAs/PRC2 axis can up regulate the KLF2 to reduce tumor progression." (PMID 37807067, 2023). "KLF2 may be of importance in the biology of malignant cells with tumor suppressive properties." (PMID 36466816, 2022).